KCTD17 (potassium channel tetramerization domain containing 17)
Description:
Substrate-adapter for CUL3-RING ubiquitin ligase complexes which mediates the ubiquitination and subsequent proteasomal degradation of TCHP, a protein involved in ciliogenesis down-regulation. Thereby, positively regulates ciliogenesis, playing a crucial role in the initial steps of axoneme extension. May also play a role in endoplasmic reticulum calcium ion homeostasis.
Synonyms: FLJ12242
Tractability: PROTAC: ubiquitination databases record sites on it; its protein half-life has been measured.
Gene: Protein-coding gene on chromosome 22 (37,051,739 to 37,063,390, forward strand). Ensembl gene ENSG00000100379.
Subcellular location: Cytoplasm
Gene Ontology:
Molecular function: cullin family protein binding; identical protein binding; protein binding; ubiquitin-like ligase-substrate adaptor activity
Biological process: endoplasmic reticulum calcium ion homeostasis; positive regulation of cilium assembly; proteasome-mediated ubiquitin-dependent protein catabolic process; protein homooligomerization
Cellular component: Cul3-RING ubiquitin ligase complex; cytoplasm; endoplasmic reticulum
Genetic constraint (gnomAD): Loss-of-function variants: 20 observed, 31.3 expected, observed/expected ratio (o/e) 0.64, 90% interval 0.45 to 0.93. The upper end of that interval is the gene's LOEUF score, 0.93, which puts it in group 3 of 6, group 1 being the genes least tolerant of losing a copy. Missense variants: 310 observed, 345.94 expected, observed/expected ratio (o/e) 0.9, 90% interval 0.82 to 0.98. Synonymous variants: 156 observed, 139.36 expected, observed/expected ratio (o/e) 1.12, 90% interval 0.98 to 1.28.
Homologues: Orthologues: chimpanzee KCTD17 (100% identical), macaque KCTD17 (88% identical), rat Kctd17 (84% identical), pig KCTD17 (83% identical), mouse Kctd17 (75% identical), guinea pig KCTD17 (73% identical), dog KCTD17 (63% identical), zebrafish kctd17 (50% identical), Drosophila melanogaster inc (36% identical), Caenorhabditis elegans inso-1 (34% identical). Paralogues in human: KCTD5 (48% identical), KCTD2 (46% identical), KCTD9 (25% identical).
Diseases named in the same sentence as KCTD17 in open-access papers:
KCTD17 is named in the same sentence as 29 diseases in open-access papers, as found by Europe PMC text mining. Sharing a sentence is not in itself a finding about the gene and the disease. The quoted sentences say what the papers report.
Dystonia (10 papers, 2016 to 2026). An abnormally increased muscular tone that causes fixed abnormal postures. "For example the KCTD17 gene mutation is characterized by a milder myoclonus affecting the upper limbs and progressive dystonia spreading from the craniocervical region to other sites." (PMID 27242657, 2016). "Specifically, the dystonia is predominant and progressive in KCTD17‐related MDS, whereas it is usually non‐progressive in SGCE‐related MDS." (PMID 37288166, 2023). "Apart from dystonia-myoclonus caused by SGCE, another mutation responsible for myoclonus-dystonia has been identified as a mutation in the KCTD17 gene." (PMID 35207493, 2022). "Given the established link between CACNA1H and the previously reported dystonia gene KCTD17 and its link with paroxysmal movement disorders, we focused our additional studies on a putative role of CACAN1H in WC." (PMID 33478561, 2021). "One candidate gene was selected for follow-up, Calcium Voltage-Gated Channel Subunit Alpha1 H, CACNA1H, due to its links with the known dystonia gene Potassium Channel Tetramerization Domain Containing 17, KCTD17, and with paroxysmal movement disorders." (PMID 33478561, 2021). "With the discovery of novel dystonia genes, such as GNAL, ANO3, KCTD17, and KMT2B, these subtypes can now be allocated to the realm of inherited forms of dystonia." (PMID 33604773, 2021). "A subset of FS symptoms, such as dystonia, myoclonus, and ataxia, may be attributed to the downregulation of PLEKHG2, DST, ARX, AAAS, KCTD17, PRDM8, and CRTC1 in FS brains as these genes are downregulated in Q84Pfs-Het brains and play a role in these movement and muscle coordination 43–49." (PMID 37398410, 2023). "Importantly, the phenotypes associated with mutations in the DYT genes enriched in the putamen ‘cyan’ module belonged to different clinical subtypes of dystonia, namely isolated dystonia (ANO3 and HPCA), combined dystonia (KCTD17 and ADCY5), and paroxysmal dystonia (KCNA1, CACNA1A, PRRT2 and SCN8A)." (PMID 32889528, 2020).
myoclonic dystonia (4 papers, 2017 to 2025). "In particular, a missense mutation of a conserved arginine (R145H) in the human Inc ortholog KCTD17 is associated with myoclonic dystonia, a movement disorder." (PMID 39841692, 2025). "Mutation of the same residue in the human Inc ortholog KCTD17 is associated with myoclonic dystonia, consistent with a critical and evolutionarily conserved function for this residue in Inc orthologs." (PMID 39841692, 2025). "KCTD17 (HGNC:25705) has already been described as an established gene associated with myoclonic dystonia (MIM #616398)." (PMID 36553572, 2022). "Human mutations at the KCTD2/ATP5H locus are associated with Alzheimer’s disease, and mutations of KCTD17 with myoclonic dystonia." (PMID 28558011, 2017). "In addition, we detected a novel heterozygous variant in the KCTD17 gene (c.508-2A>T) in a girl with a childhood-onset complex MD, mainly characterized by myoclonic dystonia." (PMID 31737037, 2019).
Obesity (2 papers, 2019 to 2023). Accumulation of substantial excess body fat. "Varying levels of evidence support their roles in neurocognitive disorders (KCTD3), neurodevelopmental disease (KCTD7), bipolar disorder (KCTD12), autism and schizophrenia (KCTD13), movement disorders (KCTD17), cancer (KCTD11), and obesity (KCTD15)." (PMID 31197948, 2019).
chronic viral hepatitis (1 paper, 2025). "This variability may reflect differences in underlying etiology—such as alcohol-related liver disease versus chronic viral hepatitis—that lead to distinct regulatory mechanisms affecting KCTD17 expression." (PMID 40744994, 2025).
ciliopathy (1 paper, 2020). A genetic disorder of the cellular cilia or the cilia anchoring structures, the basal bodies, or of ciliary function. "Because AURKA is also associated with both cancer and ciliopathy, these findings suggest that the involvement of KCTD17 and USP8 in cancer and ciliopathy might be mediated by effects on ciliogenesis via a TCHP–AURKA pathway." (PMID 32825105, 2020).
Cirrhosis (1 paper, 2025). A chronic disorder of the liver in which liver tissue becomes scarred and is partially replaced by regenerative nodules and fibrotic tissue resulting in loss of liver function. "Further investigations are warranted to characterize this subgroup in detail and to elucidate the clinical and molecular factors that underlie low KCTD17 expression in the context of severe fibrosis and cirrhosis." (PMID 40744994, 2025). "Although increased KCTD17 levels were consistently observed in both MASH-induced mouse models, a subgroup of patients with MASH or cirrhosis exhibited low KCTD17 expression." (PMID 40744994, 2025). "In addition, the histopathological examination of liver biopsies revealed a progressive increase in KCTD17 protein levels in patients with MASH and cirrhosis." (PMID 40744994, 2025). "It is also possible that the low-KCTD17 subgroup might represent cases in which compensatory mechanisms are activated in response to liver cell damage and cellular stress during the progression of MASH and cirrhosis, thereby downregulating KCTD17 in specific hepatic cell populations." (PMID 40744994, 2025).
Hepatic steatosis (1 paper, 2025). Steatosis is a term used to denote lipid accumulation within hepatocytes. "In another context, KCTD17 binds to phosphorylated PHLPP2, targeting it for ubiquitin‐mediated degradation, thereby promoting hepatic steatosis." (PMID 41000374, 2025).
liver diseases (1 paper, 2025). "Previous studies have identified KCTD17 as a significant driver to metabolic dysfunction-associated liver diseases, including MASLD, noting its upregulation in patients with MASH20,22." (PMID 40744994, 2025). "This variability raises expectations for uncovering the unknown functions and upstream regulatory mechanisms of KCTD17 in various liver diseases." (PMID 40744994, 2025).
liver fibrosis (1 paper, 2025). "In this study, we found that hepatocyte-specific Kctd17 loss-of-function or treatment with Kctd17-directed antisense oligonucleotide (ASO) reduced liver fibrosis in MASH mice fed a MASH-provoking diet." (PMID 40744994, 2025). "Our findings pave the way for future therapeutic strategies aimed at inhibiting KCTD17 or restoring SERPINA3 expression to combat liver fibrosis in patients with MASH." (PMID 40744994, 2025). "To explore the mechanisms by which Kctd17 affects liver fibrosis, we analyzed liver transcriptomic profiles and screened for hepatocyte-secreted proteins in CDAHFD-fed wild-type (WT) mice." (PMID 40744994, 2025). "In line with previous findings, our study observed lower levels of SERPINA3 or Serpina3k in both patients with MASH and mouse models, revealing an inverse relationship between KCTD17 and Serpina3k expression, which contributed to heightened liver fibrosis." (PMID 40744994, 2025). "In summary, these findings underscore the therapeutic potential of targeting KCTD17 for the treatment of MASH-induced liver fibrosis." (PMID 40744994, 2025). "Finally, we assessed the therapeutic potential of Kctd17 antagonists in treating MASH-induced liver fibrosis." (PMID 40744994, 2025). "Consequently, pharmacological inhibition of Kctd17 effectively reverses MASH-induced liver fibrosis." (PMID 40744994, 2025). "In conclusion, this study provides crucial insights into the role of KCTD17 in driving MASH-induced liver fibrosis and elucidates the mechanisms behind the reduced expression of Serpina3k/SERPINA3, as well as the functional consequences in MASH-induced mice and patients with MASH." (PMID 40744994, 2025). "Researchers studied a protein called KCTD17, which is involved in liver fibrosis." (PMID 40744994, 2025). "These patient data indicate that KCTD17 may play a role in promoting liver fibrosis during MASH pathogenesis." (PMID 40744994, 2025). "Our results demonstrate a significant increase in KCTD17 mRNA levels in patients with MASH compared with healthy individuals, with a strong positive correlation between KCTD17 expression and liver fibrosis score across varying degree of MASH severity." (PMID 40744994, 2025). "However, whether KCTD17 may influence hepatic fibrosis was unknown." (PMID 40744994, 2025). "KCTD17 depletion increased SERPINA3 levels and reduced liver fibrosis in mice fed a MASH-inducing diet by inhibiting Par2/TGFβ-mediated activation of hepatic stellate cells." (PMID 40744994, 2025). "Future studies should focus on developing specific KCTD17 inhibitors and advancing the clinical translation of SERPINA3-basaed therapies, which could provide a novel and effective treatment approach for liver fibrosis in patients with MASH." (PMID 40744994, 2025).
nonalcoholic fatty liver disease (1 paper, 2021). "KCTD17 is upregulated in the liver tissues of obese mice and nonalcoholic fatty liver disease patients; however, few studies have been published on its role in cancer." (PMID 34532296, 2021).
neurological disorders (1 paper, 2023). "For example, KCTD17 (Carpenter) and other KCTD family members regulate cyclic adenosine monophosphate signaling and are implicated in neurological disorders." (PMID 37433118, 2023).
psychiatric disorder (1 paper, 2025). A disorder characterized by behavioral and/or psychological abnormalities, often accompanied by physical symptoms. "KCTD17 encodes a protein belonging to the potassium channel tetramerization domain-containing family, which has been implicated in both neurodegenerative and psychiatric disorders." (PMID 40649837, 2025).
KCTD17 also shares sentences with these, for which no sentence is quoted: cancer (3 papers); movement disorder (3); Myoclonus (3); Alzheimer disease (1); Ataxia (1); autism (1); bipolar disorder (1); cognitive decline (1); Cognitive impairment (1); fibrosis (1); genetic disorders (1); Glucose intolerance (1); hyperekplexia (1); Insulin resistance (1); intellectual disabilities (1); paroxysmal dystonia (1); schizophrenia (1).